CREBBP (CREB binding lysine acetyltransferase )
Diseases named in the same sentence as CREBBP in open-access papers (continued):
Sharing a sentence is not in itself a finding about the gene and the disease.
medulloblastoma (8 papers, 2013 to 2025). A malignant, invasive embryonal neoplasm arising from the cerebellum. "RSTS is linked to the interstitial 16p13.3 deletion involving the CREBBP gene in around 10% of cases, increasing the risk of pediatric cancers such as medulloblastomas (MBs)." (PMID 40507954, 2025). "Heterozygous loss of CREBBP in the germline is the cause of Rubinstein-Taybi syndrome, and various benign and malignant brain tumors including glioma and medulloblastoma have been reported in those patients." (PMID 37407554, 2023). "Entities with recurrent alterations of MYCN and CREBBP are for example medulloblastoma and malignant glioma." (PMID 37407554, 2023). "Mutations in genes involved in histone acetylation – including CREBBP – are overrepresented in Sonic hedgehog (SHH)-activated medulloblastoma." (PMID 37407554, 2023). "To explore a role for CREB-complexes in medulloblastoma, we first investigated the relationship between CREBBP and EP300 mRNA expression and overall survival." (PMID 34373489, 2021). "We then grouped the medulloblastoma samples into below (or above) average pCREB Ser133 (pCREB Ser133 hi/lo), in combination with below (or above) average CREBBP (CREBBPhi/lo) or EP300 (EP300hi/lo) mRNA levels, and assessed their relationship with overall survival." (PMID 34373489, 2021). "Adult SHH-activated medulloblastomas display a higher mutation burden compared to their pediatric counterparts, particularly with mutations associated with the SHH pathway, mainly Patched1 (PTCH1) and Smoothened (SMO), as well as mutations in CREB binding protein (CREBBP), BRPF1, and TERT promoter." (PMID 37568705, 2023). "Hereto, we performed knockdown of either CREB1, CREBBP, or EP300 in MED8A cells, an in vitro model for Group 3 medulloblastoma and subsequently determined their sensitivity to the chemotherapeutic agent Etoposide." (PMID 34373489, 2021).
pancreatic cancer (8 papers, 2015 to 2026). "However, only miR-103 was directly involved in the regulation of pancreatic cancer-associated processes: E-cadherin signalling events (CDH1), TGF beta signalling pathway (TGFBR2, APC, CDH1, CREBBP, EP300, SMAD3, TSC2), and altered TFG-beta SMAD dependent signalling (TGFBR2, SMAD3, and FBXW7)." (PMID 29285254, 2017). "Consistent with the total loss of p300 function, Panc10.05 and Patu8988T cells are the only ones in a panel of pancreatic cancer cell lines that do not tolerate CREBBP knockout." (PMID 35536676, 2022). "Pathway analysis of its target genes via DAVID showed enrichment (FDR < 5 %) of genes in the Jak-Stat signaling pathway, including several receptors of interleukins (PTPN6, IL22RA1, CREBBP, IL28RA, IL15RA, PIK3R5, STAT3) and pancreatic cancer pathways (VEGFC, ACVR1B, PIK3R5, EGF, STAT3)." (PMID 26572553, 2015).
retinoblastoma (8 papers, 2016 to 2025). A malignant tumor that originates in the nuclear layer of the retina. "Emerging genes beyond RB1 (e.g., BCOR, CREBBP) highlight the expanding genetic landscape of retinoblastoma." (PMID 41009976, 2025). "Together with JUN, CREBBP is also involved in cell division and cell proliferation, and it is upregulated by the oxidative stress response in retinoblastoma cells." (PMID 32609278, 2020). "Genes such as BCOR, CREBBP, ATRX, SMARCB1, and ARID1A, which are involved in chromatin remodeling, transcriptional regulation, or DNA repair, have been found to be mutated or dysregulated in some retinoblastoma tumors." (PMID 41009976, 2025). "However, no alterations were encountered in recurrently mutated genes in RB1−/− retinoblastoma, such as BCOR or CREBBP." (PMID 32971811, 2020). "BCOR and CREBBP should be included, along with RB1, in any future targeted sequencing in order to maximise the capture of recurrent non-RB1 genetic variations within retinoblastoma patients." (PMID 33805427, 2021).
colorectal cancer (7 papers, 2019 to 2026). A primary or metastatic malignant neoplasm that affects the colon or rectum. "In bladder and colorectal cancers, mutated tumors consistently exhibited longer OS than WT CREBBP/EP300 cases, with median OS not reached within the follow-up period in the mutated groups." (PMID 41301688, 2025). "In addition to TET1 and RNF43, our study also identified an association between NCOA3, CREBBP, and NOTCH3 mutations and improved survival in colorectal cancer patients." (PMID 35798829, 2022). "In this study, we demonstrated that the expression of CREBBP mRNA was correlated with CRC metastasis in a set of colorectal carcinomas with or without F. nucleatum infection." (PMID 30951563, 2019).
hepatocellular carcinoma (7 papers, 2020 to 2024). A malignant tumor that arises from hepatocytes. "In addition, previous data have detected loss of heterozygosity at the EP300 or CREBBP loci in colorectal, gastric, ovarian, and hepatocellular carcinomas." (PMID 32493417, 2020). "CREBBP stimulates tumor cell growth in hepatocellular carcinoma and positively modulates angiogenesis." (PMID 35281474, 2022).
melanoma (7 papers, 2016 to 2024). A malignant, usually aggressive tumor composed of atypical, neoplastic melanocytes. "We first determined the expression levels of EP300 and CREBBP across a panel of melanoma cell lines that were either sensitive or resistant to BRAFi therapy and found that cell lines that were sensitive to inhibitor therapy had increased EP300 levels." (PMID 38030596, 2023). "Co-treatment of BRAF-mutant melanoma cell lines with the EP300/CREBBP inhibitor I-CBP112 decreased the sensitivity of the melanoma cells to BRAFi, increasing the number of colonies formed." (PMID 38030596, 2023).
multiple myeloma (7 papers, 2020 to 2025). "Other studies of CREBBP/EP300 inhibition show similarly modest changes in chromatin accessibility in both multiple myeloma and embryonic stem cells, but this phenomenon has not been observed in hormone-dependent cancers." (PMID 35353838, 2022).
ovarian carcinoma (7 papers, 2006 to 2023). A malignant neoplasm originating from the surface ovarian epithelium. "CREBBP knockdown in ovarian cancer cells significantly inhibited tumor proliferation both in vitro and in vivo." (PMID 34149923, 2021). "Taken together, the results indicated that CREBBP knockdown promoted chemo-sensitivity, which was correlated with the enhanced apoptosis in ovarian cancer cells." (PMID 34149923, 2021). "Knockdown of CREBBP by shRNA significantly suppressed tumor proliferation in ovarian cancer cells both in vitro and in vivo." (PMID 34149923, 2021). "Taken together, CREBBP knockdown significantly suppressed tumor proliferation in ovarian cancer cells." (PMID 34149923, 2021). "As apoptosis is crucial in the regulation of cellular proliferation and chemo-sensitivity, Annexin V-PI staining was performed to verify the effect of CREBBP knockdown on apoptosis in ovarian cancer cells." (PMID 34149923, 2021). "All the cumulated evidences indicate the affected CREBBP codon as a highly polymorphic site, resulting in a aminoacidic change which does not disrupt protein function sufficiently to cause RSTS or to predispose to breast and/or ovarian cancer." (PMID 17052327, 2006). "Furthermore, CREBBP knockdown also enhanced the sensitivity of ovarian cancer cells to CDDP." (PMID 34149923, 2021). "Moreover, CREBBP knockdown promoted chemo-sensitivity in ovarian cancer cells." (PMID 34149923, 2021). "In the present study, we utilized shRNA targeting CREBBP to inhibit CBP expression and examined its effect on ovarian cancer cells." (PMID 34149923, 2021). "CREBBP, in short CBP, has been reported to be involved in tumorigenesis in various cancers, but its role in ovarian cancer remains largely unexplored." (PMID 34149923, 2021). "In our study, we demonstrated that knockdown of CREBBP dramatically decreased PERK/ATF4/STC2 expression, and promoted apoptosis in ovarian cancer cells treated with CDDP." (PMID 34149923, 2021). "In our study, survival analysis of CBP in patients with ovarian cancer was conducted using the Kaplan-Meier Plotter database, then we utilized specific shRNA targeting CREBBP to block the expression of CBP, and detected its effect on cell proliferation and chemo-sensitivity in ovarian cancer cells." (PMID 34149923, 2021).
glioblastoma (6 papers, 2006 to 2023). The most malignant astrocytic tumor (WHO grade IV). "All the mutations in CREBBP were in samples from high-risk patients, and comprised two glioblastomas and three astrocytomas." (PMID 33718432, 2021). "Inhibitors of HSP90 (17-AAG) and CREBBP (ICG-001) have recently shown effects in glioblastoma and other cancer models/cell lines." (PMID 31386654, 2019). "We also noted what appeared to be distinct expression profiles for each tissue type (for example compare expression of CREBBP in glioblastomas versus renal cancers)." (PMID 16638127, 2006). "miR-181d exerts antitumor effects in glioblastoma by targeting CREBBP." (PMID 35281474, 2022).
Alzheimer disease (5 papers, 2015 to 2025). A progressive, neurodegenerative disease characterized by loss of function and death of nerve cells in several areas of the brain leading to loss of cognitive function such as memory and language. "In Alzheimer’s disease, dysregulation of CREBBP has been linked to synaptic plasticity alterations." (PMID 38002524, 2023). "Among the differentially expressed proteins, there were proteins involved either in the neurogenic process (e.g. GDF11) or in Alzheimer’s disease (e.g. LRRK2, RCAN1, NTRK2), or in both neurogenesis and Alzheimer’s disease (e.g. CREBBP, SFRP1, IL1RAP)." (PMID 36703180, 2023).
brain tumors (5 papers, 2020 to 2024). "In this report, we describe the radiological, histopathological, immunohistochemical, and molecular features of another brain tumor that features a CREBBP::BCORL1 fusion, co-occurring with pathogenic mutations in BCOR and CREBBP." (PMID 38216991, 2024). "We conclude that combined loss of CREBBP and overexpression of MYCN in NSCs induces brain tumor formation with early postnatal manifestation and specific location in the OB." (PMID 37407554, 2023). "In contrast, CREBBP loss or MYCN overexpression alone in hGFAP-positive cells does not induce malignant brain tumors, as previously reported, indicating that tumorigenesis in hGFAP-cre::CrebbpFl/Fl::lsl-MYCN mice depends on concurrent alterations in both genes." (PMID 37407554, 2023). "CREBBP is a tumor suppressor, whose decreased expression cooperates with the oncogene MYCN to induce malignant brain tumors in mice." (PMID 39043735, 2024). "Besides, five additional inputs were found after searching for alterations in BCOR, BCORL1, EP300, TRAP1, CREBBP, and L3MBTL2 in the repository of 23 published studies on neuroepithelial brain Tumors including 7207 samples of 6761 patients." (PMID 38637838, 2024).
meningioma (5 papers, 2020 to 2024). A generally slow growing tumor attached to the dura mater. "Among these genes, NF2 frameshift mutation (c.503delC:p.K170Rfs*43) in M1 and CREBBP frameshift mutation (c.3923delT:p.L1308Cfs*30) in M2 were highlighted upon comparison with previously published data on genes mutated in at least two cases of meningiomas." (PMID 39066986, 2024). "Furthermore, we identified SNV/INDELs unique to each focus, with NF2 mutation prevalent in the transitional meningioma and CREBBP mutation in the chordoid meningioma." (PMID 39066986, 2024). "With regards to meningiomas, a recent study identified CREBBP as present in aggressive meningiomas." (PMID 36514795, 2022). "CREBBP, PIK3CA (R108H), PIK3R1, BRCA1, and SMARCB1 are the most represented mutations; unfortunately, none of these mutations can predict the rate of recurrence in NF2-mutated meningiomas." (PMID 35892898, 2022).
Obesity (5 papers, 2012 to 2025). Accumulation of substantial excess body fat. "The NGS analysis revealed four variants related to obesity: SIM1, SEMA3C, PLXNA4, and CREBBP gene mutations." (PMID 40428410, 2025). "Inhibition of hypothalamic CREBBP results in profound obesity, impaired glucose homeostasis, and increased food intake." (PMID 31870441, 2019). "Also, CREBBP is related to obesity, and it is a transcriptional coactivator involved in neuroplasticity and the regulation of metabolism in the hypothalamus." (PMID 40428410, 2025). "Moreover, C‐C motif chemokine 2 (CCL2) and KDM6A expression was higher in the group with obesity, as were CREBBP and EP300." (PMID 40518865, 2025). "Specifically, we observed elevated levels of KDM6A, CREBBP, and EP300 histone modifiers in ASCs from patients with obesity class II‐III." (PMID 40518865, 2025). "In the vWAT progenitor cells (ASCs), there was a substantial increase in CCL2 and an increase in the expression of KDM6A, as well as the acetylases CREBBP and EP300 in the patients with obesity." (PMID 40518865, 2025). "We hypothesize that obesity modulates histone H3K27 marks, modified by demethylases (lysine‐specific demethylase 6A and 6B [KDM6A/KDM6B]) and acetylases (CREB–binding protein [CREBBP]/histone acetyltransferase EP300), affecting ASC function." (PMID 40518865, 2025).
triple-negative breast carcinoma (5 papers, 2019 to 2025). An invasive breast carcinoma which is negative for expression of estrogen receptor (ER), progesterone receptor (PR), and human epidermal growth factor receptor 2 (HER2). "Consistent with previous results, CREBBP/EP300 HAT inhibition shows activity in a subset of triple negative breast cancer (TNBC) cell lines, but we also noticed potent growth inhibition in ER+ cell lines." (PMID 35353838, 2022). "Analysis of gene expression using bc-GenExMiner showed that the mRNA levels of FABP, ADIPOQ, PPARG, CD36, PPARGC1A, and CREBBP were significantly lower in basal-like and triple-negative breast cancer (TNBC) cells than in non-basal-like and non-TNBC cells." (PMID 36114448, 2022).
cervical cancer (4 papers, 2017 to 2023). A primary or metastatic malignant neoplasm involving the cervix. "In support to the previous findings, the present study found that both CREBBP and p300 were up-acetylated in cervical cancer tissues compared with adjacent normal tissues, suggesting a potential role of CREBBP/p300 in cervical carcinogenesis." (PMID 32489318, 2020). "More importantly, our acetylome analysis and IP experiments demonstrated that CREBBP and p300 were up-acetylated in cervical cancer tissues compared with adjacent normal tissues." (PMID 32489318, 2020). "Furthermore, EP300, ARID1A, FBXW7, NFE2L2, PIK3CA, and ERBB2 have all been previously reported as pathogenic genes in cervical cancer, and we highlighted the roles of MLL2, MLL3, and CREBBP in the tumorigenesis." (PMID 28390392, 2017). "In particular, seven genes showed higher expression in cervical cancer and positively correlated with EMT scores, including CSRP2BP, LPCAT1, NAT14, CREBBP, MSL3, ATF2 and GNPNAT1." (PMID 37845756, 2023). "Consistent with the acetylome results, CREBBP and S100A9 were up-acetylated in cervical cancer tissues compared with adjacent normal tissues." (PMID 32489318, 2020). "Furthermore, the acetylated levels of CREBBP and S100A9 in cervical cancer tissues were confirmed by immunoprecipitation (IP) and Western blot analysis." (PMID 32489318, 2020).
liver fibrosis (4 papers, 2012 to 2023). "Among others, we identified CREB-binding protein (CREBBP) as a possible target gene for miR-571, a gene involved in general transcriptional regulation previously associated with the regulation and pathogenesis of liver fibrosis." (PMID 22412969, 2012). "In addition, studies have shown that Smad2 and Smad3 may also participate in the general transcription mechanism through direct interaction with p300 and CREBBP, and may participate in the development of liver fibrosis through the transcription of extracellular matrix." (PMID 36727157, 2023).
lung adenocarcinoma (4 papers, 2015 to 2026). A carcinoma that arises from the lung and is characterized by the presence of malignant glandular epithelial cells. "CREBBP mutations are observed in various types of cancers including lung adenocarcinoma and are involved in carcinogenesis and progression." (PMID 37864465, 2024). "Additionally, brain metastases of lung adenocarcinoma with mutation in CREBBP have been shown to be associated with poorer prognosis compared to wild-type." (PMID 36514795, 2022).
microcephaly (4 papers, 2019 to 2025). A congenital or acquired developmental disorder in which the circumference of the head is smaller than normal for the person's age and sex. "Rather, her features, with short stature, microcephaly, renal anomaly, and scoliosis, recalled the phenotype of the Menke–Hennekam syndrome 1 (#618332) associated with missense mutations in the distal exons of CREBBP." (PMID 33337535, 2021).
myelodysplastic syndrome (4 papers, 2016 to 2023). A clonal hematopoietic disorder characterized by dysplasia and ineffective hematopoiesis in one or more of the hematopoietic cell lines. "Perturbations in CREB binding protein (CREBBP) are associated with hematopoietic malignancies, including myelodysplastic syndrome (MDS)." (PMID 27427906, 2016).
neuroblastoma (4 papers, 2017 to 2024). Neuroblastoma (NB) is the most common solid, extracranial childhood tumor. "From the library’s lead compounds, we further evaluated CBP/p300 bromodomain inhibitors as potential MYCN amplified neuroblastoma therapeutics, since CBP (CREBBP) was prominent in our MYCN-related -omic and neuroblastoma patient outcome analysis." (PMID 33968920, 2021). "Interestingly, several sequence alterations in other genes involved in chromatin regulation in neuroblastoma have been found, including EP300, CREBBP, TTF2, KDM5A, CHD9, and gene IKZF1, which might undergo somatic mutations and promote NB occurrence." (PMID 28055978, 2017).
Rubinstein-Taybi syndrome 1 (4 papers, 2020 to 2025). "The classic Rubinstein-Taybi syndrome Type 1 (RSTS1, OMIM 180849) is caused by heterozygous mutations or deletions of the CREBBP gene." (PMID 32181026, 2020). "This includes a complex rearrangement of OCA2 (MIM# 611409) with deep intronic breakpoints and deletion of the second exon of CREBBP (MIM# 600140) in a child with features of Rubinstein-Taybi syndrome 1 (MIM#180849) and previous negative ES." (PMID 39763557, 2025).
astrocytoma (3 papers, 2020 to 2024). "We also present four adult diffuse glioma cases including GBM, IDH-Wildtype and Astrocytoma, IDH-Mutant with CREBBP fusions and describe the necessity of complementary molecular analysis in “CNS tumor with BCOR/BCOR(L1)-alterations for securing a final diagnosis." (PMID 38637838, 2024). "Knowing that adult diffuse gliomas such as GBM, IDH-Wildtype and Astrocytoma, IDH-Mutant may present CREBBP fusions, it is of utmost importance to take additional molecular findings and the histomorphology into account while interpreting the results." (PMID 38637838, 2024).